TNF (tumor necrosis factor)
Diseases named in the same sentence as TNF in open-access papers (continued):
Sharing a sentence is not in itself a finding about the gene and the disease.
hyperlipidemia (continued). "It was hypothesized that proinflammatory cytokines from GCF or systemic circulation, such as TNF-α, IL-1β, and IL-6, induce hyperlipidemia due to enhanced hepatic lipogenesis, increased synthesis of triglycerides, and reduced clearance of both triglycerides and LDL." (PMID 36983201, 2023). "In addition, GLXB treatment could also reduce the levels of IL6 and TNF-α in the serum of hyperlipidemia rats." (PMID 36120369, 2022). "On the other hand, the hyperlipidemia status would lead to the inflammatory reaction in which the adipokines would trigger a low-grade chronic inflammation status via activating the secretion of monocyte chemotactic protein, tumor necrosis factor, and interleukin." (PMID 33401577, 2021). "To test whether hyperlipidemia sharpened the inflammatory response induced by myocardial I/R through the up-regulation of the secretion of pro-inflammatory cytokines, we analyzed the expression of pro-inflammatory cytokines TNF-α and IL-1β in serum." (PMID 27731393, 2016). "In studies with sea buckthorn berry extract, the polyphenols significantly reduced serum levels of TNF-α and IL-6 and also alleviated vascular impairment by decreasing the expression of eNOS and ICAM-1 in the aortas of rats with hyperlipidemia." (PMID 41156509, 2025). "TNF-a can inhibit the lipogenic activity of several lipases, including LPL, inhibit lipid synthesis and reduce LPL mRNA expression, while leading to hyperlipidaemia." (PMID 37533569, 2023). "After exploring the PPI network of DO for hyperlipidemia, the key targets of DO for hyperlipidemia included AKT1, TNF, PPARG, ADIPOQ, and APOB." (PMID 35502176, 2022). "Moreover, hyperlipidemia–induced dysbiosis can lead to disorder of the local immune system, accompanied by production of inflammatory cytokines such as IL–1β, IL–6, and tumor necrosis factor (TNF)–α, and adipokines such as leptin in addition to increasing the intestinal permeability." (PMID 36364184, 2022). "This showed that XOS increased the level of anti-inflammatory factor IL-10 and reduced the levels of pro-inflammatory factors TNF-α, IFN-γ, and IL-6 in the serum, thus exerting a regulatory effect on the blood lipid levels of mice with hyperlipidemia." (PMID 34880767, 2021). "In conclusion, the effect of SP-FJG in regulating glucose tolerance, TNF-α, IL-6, FINS, and hyperlipidemia was better than using SP individually in ZDF rats." (PMID 32351607, 2020). "Treatment with SREBP decoy ODN remarkably decreased the expression of TNF-α, IL-1β, and IL-8, more than the Scr decoy ODN did in HFD-induced hyperlipidemia mice." (PMID 31952262, 2020). "Our research also proved that fed Wistar rats with high-fat diet up-regulated the expression of TNF-α and TGF-β1, suggesting the inflammatory factor TNF-α and TGF-β1 were activated in a hyperlipidemia circumstance." (PMID 29569980, 2018). "Biochemical analysis of mice serum in hyperlipidemia mice displayed augmented levels of parathyroid hormone (PTH), tumor necrosis factor-α (TNF-α), C-terminal telopeptide of type-1 collagen (CTX; a bone resorption marker), calcium, and phosphorus." (PMID 27338453, 2016). "We also investigated the correlation between inflammation markers and lipidemia and found that the levels of hs-CRP, TNF-α, SAA, and uMCP-1 were positively correlated with TC and LDL-C and had no statistical significance with TG and HDL-C." (PMID 24350298, 2013). "Pro-inflammatory cytokines such as tumor necrosis factor-α (TNF-α) reduce insulin sensitivity in muscle tissue and stimulate hepatic lipogenesis and hyperlipidemia." (PMID 21738773, 2011). "In case of liver inflammation related genes (IL-1β, TNF-α, IL-6, IL-18, CCL20, and NF-κB) their expression levels were significantly (P < 0.05) upregulated and IL-1RN was significantly (P < 0.05) downregulated in the liver of hyperlipidemia group." (PMID 41144456, 2025).
hyperlipidemia (continued). "Besides oxLDL stimulation, we harvested the HFD‐fed mouse serum including hyperlipidemia to treat MPMs and found that WEE1 deletion inhibited hyperlipidemia‐induced TNF‐α and IL‐6 levels in cultured MPMs." (PMID 40202104, 2025). "In fact, TNF-α amniotic acid together with increased IL-1β results in increased protein kinase C (PKC), the destruction of pancreatic β-cells and a synergistic increase in hyperlipidemia through lipid clearance, increased lipogenesis and decreased lipolysis." (PMID 40141192, 2025). "Therefore, investigating the relationship between inflammation and hyperlipidemia using other inflammatory markers, including high-sensitivity CRP, TNF-α, and IL-1β, is necessary." (PMID 40552326, 2025). "Formerly, data suggested that inflammatory cytokines (TNFα and IL-6) may have a suppressive effect on SDF-1 in male patients with hyperlipidemia." (PMID 37894988, 2023). "In summary, AKT1, TNF, PPARG, ADIPOQ, and APOB may be targets for the action of DO in the treatment of hyperlipidemia." (PMID 35502176, 2022). "The network analysis uncovered that naringenin, isorhamnetin, and taxifolin might be the compounds in DO that are mainly in charge of its roles in hyperlipidemia and might play a role by modulating the targets (including PPARG, ADIPOQ, AKT1, TNF, and APOB)." (PMID 35502176, 2022). "For instance, baicalin could regulate the gene expression of SLC2A1, TNF, NFKB1, SREBF1, and CASP3 to ameliorate obesity and hyperlipidemia through a network pharmacology approach." (PMID 36425260, 2022). "HFD induces hyperlipidemia proven by increased plasma concentration of CT, LDL-C, and TG, which initiates an inflammatory response, supported through increased inflammatory biomarkers (hs-PCR, TNF-α, IL-1β, IL-6) compared to the BD group." (PMID 35204113, 2022). "Oral administration of SVP in T2DM mice also could improve the diabetic complications of hyperlipidemia and inflammation response, indicating as lower concentrations of TC, TG, LDL-c, FFA, TBA, TNF-α, IL-6, and higher levels of IL-10 in serum." (PMID 36337615, 2022). "In addition, inflammatory molecules and apoptosis-related proteins, such as IL-6, TNF-α, and BAX, were abnormally elevated in patients with hyperlipidemia." (PMID 34307504, 2021). "Our single cell RNA-Seq data analysis results showed that CD95, TNF-α and IL-1β are co-expressed in CD95+ monocytes and macrophages in aortas and peripheral blood, and CD95 expressions are increased in MHO aortas in hyperlipidemia conditions." (PMID 33488632, 2020). "In summary, it was found that hyperlipidemia significantly aggravated the level of TG in the brains of rats fed a CCT diet, which stimulated astrocytes to release inflammatory cytokines TNF-α and IL-1, which had direct toxic effects on the cerebral vessels and neurons." (PMID 28143622, 2017). "High-fat diet induced hyperlipidemia worsened MI/R mediated heart injury (elevation of infarct size, CK-MB and LDH activity), activated TLR4 over-expression in hearts, released inflammatory cytokines (LPS, TNF-α and IL-1β) excessively." (PMID 27731393, 2016). "Furthermore, the expression levels of the inflammatory transcription factors, tumor necrosis factor-α and interleukin-6, were shown to be reduced in the XZK group when compared with the hyperlipidemia group." (PMID 25371725, 2014). "The hyperglycemic state and hyperlipidemia in turn activate glycation end products (AGEs), whose receptors are on monocytes, endothelial cells and macrophages, which secrete interleukin 1β (IL-1β), interleukin 6 (IL-6), Prostaglandin E2 (PGE2) and tumor necrosis factor alpha (TNF-α)." (PMID 40141192, 2025). "In our study, the HLD induced hyperlipidemia, which is highlighted by higher serum levels of TC, LDL-C, and initiated an inflammatory process shown by higher serum levels of inflammation markers (hs-PCR, TNF-α, IL-1β, IL-6) in the HLD group compared to the group fed with SD." (PMID 34300308, 2021).
hyperlipidemia (continued). "In addition, SREBP decoy ODN decreased AST, ALT, total cholesterol, and triglyceride levels in the serum of hyperlipidemic mice fed with HFD, and furthermore, significantly inhibited the pro-inflammatory cytokine expressions of IL-6, TNF-α, IL-1β, and IL-8 in HFD-induced hyperlipidemia mouse models." (PMID 31952262, 2020). "In hyperlipidemia, IL‐1β, IL‐6, IL‐8, and IL‐10 still had significant differences between the SAP group and non‐SAP group (p < .05), while IL‐5, IL‐17, TNF‐α had no statistical differences between the two groups." (PMID 38411379, 2024). "Moreover, HLF could significantly reduce the levels of NLRP3, caspase-1, IL-1β, IL-6, IL-18, and TNF-α and increase the activities of plasma SOD, CAT, and GSH-PX, which suggested that HLF could effectively relieve the inflammatory response and oxidative stress induced by hyperlipidemia." (PMID 36425260, 2022). "Interestingly, TNFα and IL-1β have also been shown to induce VCAM-1 expression by this pathway and may account in the absence of hyperlipidemia but under hyperglycemic conditions (such as in the diabetic wt mice in this study), for the observed up-regulation of VCAM-1 in retinal vessels." (PMID 20856927, 2010).
kidney damage (166 papers, 2008 to 2025). "Rhabdomyolysis‐induced muscle damage leads to the release of myoglobin into the bloodstream, which causes kidney damage, generates free radicals, and elevates proinflammatory cytokines such as TNF‐α." (PMID 39803217, 2025). "AKI has been linked to changes in DNA methylation and histone modification which results in altered transcription of genes linked to kidney damage, including tumor necrosis factor (TNF)." (PMID 36766754, 2023). "The potential target selection was narrowed down to kinases that have previously been detected in endothelial cells, and had been linked to inflammation, TNF-α-signalling or kidney damage." (PMID 36532777, 2022). "Accordingly, TNF-α inhibitors can ameliorate renal dysfunction and reduce the structural damage caused by cisplatin, and inhibition of TNF-α more effectively reduce cisplatin-induced than IR-induced kidney damage." (PMID 34149721, 2021). "In cisplatin-induced AKI, IL-4 and TNF-α activate iDCs into mature phenotypes at the initial stage, causing kidney damage." (PMID 34149721, 2021). "We have shown that serum levels of insulin like growth factor binding proteins (IGFBP), TNF-α and IL-6 pathways were able to stratify T1D patients into risk categories for a number of complications, including nephropathy and retinopathy." (PMID 33868296, 2021). "The aim was to explore the association between the TNF-α promoter -1031T/C single nucleotide polymorphism (SNP) and the serum TNF-α level in addition to nephropathy among type 2 diabetic patients." (PMID 32684830, 2020). "It has been shown that tumor necrosis factor-α (TNF-α) levels are associated with the development of nephropathy." (PMID 32481556, 2020). "A high-fat diet activates the inflammatory response by increasing TNF-α expression in the kidney, thus causing kidney damage in obese humans and animal models." (PMID 33050202, 2020). "As a case in point, a study has shown that monocyte chemoattractant protein-1 (MCP-1) could stimulate the synthesis and release of TNF-α and IL-6 in renal cells, initiate programmed inflammation and further cause kidney damage." (PMID 35054932, 2022). "Therefore, this study is an attempt to explore the association between the -1031T/C SNP of TNF-α and the susceptibility to develop nephropathy in patients with T2DM." (PMID 32684830, 2020). "Pro-inflammatory cytokines (TNF-α, IL-6) enhance metabolic stress, leading to progressive kidney damage." (PMID 40698245, 2025). "Our study results demonstrated that the injection of 50% glycerol (10 ml/kg, I.M) led to changes in biochemical factors, increased oxidative stress markers, upregulated the expression of NGAL and TNF-α proteins, and consequently induced kidney damage." (PMID 40271506, 2025). "Pro-inflammatory cytokines like IL-1β and TNF-α further drive kidney damage by increasing ferritin expression and disrupting iron balance." (PMID 41445831, 2025). "Studies have shown that TNF-α and IL-6 are involved in the pathogenesis of LN, promoting inflammatory responses and exacerbating kidney damage." (PMID 40573311, 2025). "CsA-induced kidney damage was halted by sitagliptin and hesperidin via increasing Nrf2 and suppressing TNF-α, NF-κB, and Bax." (PMID 40867921, 2025). "As a result, it seems probable that TNF-α contributes to the progression of nephropathy, especially when there is evidence of protein leakage." (PMID 38765394, 2024). "Abdominal obesity is linked to the production of inflammatory cytokines and adipokines, such as TNF-α, IL-6, adiponectin and leptin, which can be involved in kidney damage." (PMID 38559695, 2024). "Proinflammatory cytokines, including IL-1β, TNF-α, and IL-6, are mediators of kidney injury, and the downregulation of inflammatory cytokines supported strain 44XBT-induced alleviation of kidney damage." (PMID 38814072, 2024).
kidney damage (continued). "Here, we confirmed the activation of inflammation in ADR-induced nephropathy, as evidenced by increased phosphorylation of p65-NF-κB and elevated TNF-α levels in kidneys and circulation." (PMID 39408958, 2024). "Here, to mimic TNFα stimulation of proinflammatory events during nephropathy, we treated human normal organoids derived from kidney tissue with TNFα and determined the TNFα-driven changes observed in these organoids." (PMID 39871891, 2024). "Increased TNF-α levels in cisplatin-induced kidney damage are accompanied by rises in IL-8, IL-1β, and IL-18, further promoting inflammation and damage." (PMID 39599345, 2024). "More importantly, AUDA treatment inhibited renal NF-κB activation and reduced TNF-α levels in rats with ADR-induced nephropathy." (PMID 39408958, 2024). "Inhibiting TNF-α with pharmacological agents or antibodies significantly reduces the production of other cytokines and kidney damage." (PMID 39599345, 2024). "CLP induction led to SA-AKI, as indicated by elevated serum levels of malondialdehyde, tumor necrosis factor-alpha, urea nitrogen, creatinine, and neutrophil gelatinase-associated lipocalin (NGAL), along with histopathological features of kidney damage." (PMID 39594541, 2024). "An intraperitoneal injection of LPS (5 mg kg−1) resulted in increased plasma TNF-α levels and kidney damage." (PMID 37353597, 2023). "Some proinflammatory factors such as TNF‐α not only promote cell apoptosis and enhance kidney damage, but also activate inflammatory signaling pathways such as STAT3 and NF‐κB to trigger the inflammatory response." (PMID 35734954, 2022). "To prove that fucoidan nanoparticles are involved in regulating inflammatory cytokines in streptozotocin-induced kidney damage in diabetic rats, we measured the inflammatory cytokines level of IL-6 and TNF-α." (PMID 35685736, 2022). "The blood levels of IL-6, TNF-α, and endostatin released by kidney damage increased with age, especially in KK-Ay/TaJcl mice when compared with the control." (PMID 36289909, 2022). "PFD treatment significantly inhibited the expression of TNF-α, IL-6, and nitric oxide synthase-2 by M1 macrophages, suggesting its efficacy in the early and late periods of kidney damage." (PMID 33520317, 2021). "The inhibition of p38 MAPK reduces the production of TNF-α, thereby effectively protecting against cisplatin-induced kidney damage." (PMID 33750909, 2021). "TNF-α activates proinflammatory cytokines and chemokines to trigger oxidative stress, ultimately exacerbating kidney damage." (PMID 33750909, 2021). "The levels of IL-11 increase.Inhibition of IL-18 can significantly prevent kidney damage.CCL5 and IL-1α slightly increase.Inhibition of TNF-α cannot significantly reduce kidney damage.NLRP3 pathway is the key pathogenesis of inflammation." (PMID 34149721, 2021). "The RAGE ligand HMGB1 also plays a causal role in renal inflammation by enhancing ERK1/2, TNF-α, interleukin (IL)-6, and MCP-1, leading to nephropathy and chronic kidney disease." (PMID 33568752, 2021). "Chronic inflammation and proinflammatory cytokines, such as TNF-alpha are the possible links between active inflammation and kidney damage." (PMID 34134686, 2021). "Pro administration attenuated rI/R-induced kidney damage and renal TNF-α, IL-6, and CXCL-10 expression." (PMID 34111028, 2021). "NF-κB is a transcription factor that induces the production of proinflammatory factors, such as IL-1β and TNF-α and subsequent kidney damage." (PMID 33551679, 2021). "Our results on the serum level of sTNFRI and sTNFRII are in agreement with previous report showing activation of TNF-α system in T1D patients with nephropathy, retinopathy and neuropathy." (PMID 33868296, 2021).